TLR4 (toll like receptor 4)
Diseases named in the same sentence as TLR4 in open-access papers (continued):
Sharing a sentence is not in itself a finding about the gene and the disease.
Insulin resistance (533 papers, 2008 to 2026). Increased resistance towards insulin, that is, diminished effectiveness of insulin in reducing blood glucose levels. "In patients with T2DM, the increased expression of TLR2, TLR4, and plasma LPS is associated with plasma insulin concentration and insulin resistance." (PMID 40076851, 2025). "Beyond lipid metabolism, fetuin-A has been implicated in promoting insulin resistance by inhibiting insulin receptor tyrosine kinase activity, and in amplifying systemic inflammation through activation of Toll-like receptor 4 pathways." (PMID 41007661, 2025). "TLR4 deficiency has protective effects on insulin resistance in mice, but TLR4 polymorphisms in humans increase the risk of T2DM." (PMID 40076851, 2025). "In these studies, it was not defined if circulating FN was the ‘classic pFN’ or cellular, EDA‐FN (from tissues) which was recently linked to systemic inflammation and insulin resistance via activation of Toll‐like receptor 4 (TLR4)." (PMID 39054559, 2024). "Studies have demonstrated that TLR4 deficiency can alleviate inflammation and insulin resistance in adipose tissue, and inhibit liver steatosis." (PMID 38275739, 2024). "In contrast, TLR4 deficiency and pharmacological inhibition of TLR4 improve disturbed wound healing in high-fat diet-induced obese mice with insulin resistance." (PMID 39337466, 2024). "The mechanism through which TLR4 induces insulin resistance involves the increased transcription of genes associated with ceramide synthesis via IKKβ and NF- κB." (PMID 38379904, 2024). "Then, when this activation occurs, TLR-4 induces pro-inflammatory cytokine release, most of them associated to insulin resistance, promoting type 2 diabetes." (PMID 38541047, 2024). "When LPS binds to TLR-4, it recruits intracellular adaptor proteins, which leads to the activation of proinflammatory kinases associated with insulin resistance." (PMID 39683552, 2024). "The innate immune factor TLR4 is associated with inflammation and glucolipid metabolism, which is linked to insulin resistance, glycolysis, pyruvate oxidative decarboxylation, adipogenic gene expression, and intestinal permeability and flora." (PMID 38275739, 2024). "In the setting of periodontitis, overexpression of TLR4 has been connected to diseases, including insulin resistance and glucose intolerance, which are both linked to heightened inflammatory responses." (PMID 39063437, 2024). "In the context of obesity, a risk factor for T2DM, TLR4 causes insulin resistance and metabolic inflammation through the upregulation of proinflammatory genes’ transcription and the activation of the proinflammatory kinases JNK, IKK, and p38." (PMID 37371102, 2023). "Increasing evidence suggests that hepatocyte TLR4 plays an important role in regulating obesity-associated glucose dysregulation and insulin resistance in mice." (PMID 36979389, 2023). "Acute exposure to LPS can cause transient hypoglycemia and insulin resistance by inhibiting hepatic glucose production through the TLR4, MyD88, and NFκB pathways." (PMID 35622768, 2022). "Toll-like receptor 4 (TLR4) is linked to metabolic inflammation and insulin resistance in obese people and OA patients." (PMID 36097281, 2022). "AdipoRon ameliorated insulin resistance, fibrosis, M1-dominant inflammation, and apoptosis in association with reduced accumulations of free fatty acid, triglycerides, and TLR4-related ceramide in the heart." (PMID 35351872, 2022). "Extra domain A of cellular fibronectin (FN-EDA) is known to cause insulin resistance, atherosclerosis, tissue fibrosis, ischemic stroke and exaggerated myocardial reperfusion injury through Toll-like receptor 4 (TLR4)." (PMID 35690624, 2022). "Much evidence has demonstrated critical roles for TLR4 in regulating obesity-associated inflammation and systemic insulin resistance." (PMID 34943809, 2021).
Insulin resistance (continued). "In particular, activation of Toll-like receptor (TLR)-2 and TLR-4 is associated with obesity-mediated insulin resistance and the pathogenesis of metabolic diseases." (PMID 34832960, 2021). "Activated LPS/TLR4 signaling in Kupffer cell causes insulin resistance through inhibition of insulin receptor substrate-1 phosphorylation in the liver." (PMID 32149099, 2020). "Haplotype analysis of TLR4 D299G/T399I showed that GT carriers had a significant association with increased probability of insulin resistance (odds ratio = 4.73; 95% CI 1.19–18.90; p-value = 0.016)." (PMID 32708841, 2020). "We determined the role of cellular fibronectin (CFN) containing the alternatively spliced extra domain A (FN-EDA) in causing insulin resistance (IR) through toll-like receptor 4 (TLR4)." (PMID 32499562, 2020). "TLR4 activation triggers the upstream regulator of inflammatory pathways linked to the generation of insulin resistance, such as SOCS3, NF-κB and JNK." (PMID 32708841, 2020). "Increased concentration of IL-6, secreted by adipocytes and monocytes and activated through the TLR4-NF-κB pathway, has been classically associated with proinflammatory responses and insulin resistance in obesity." (PMID 32604889, 2020). "In contrast, a study conducted in C3H/HeJ mice, which have a spontaneous TLR4 loss-of-function mutation, demonstrated that these mice are protected from diet-induced insulin resistance and weight gain." (PMID 32947825, 2020). "TLR4-deficient mice fed with a HFD exhibit improved insulin resistance, reduced tissue inflammation, and decreased M1 macrophage infiltration." (PMID 31582899, 2019). "Previous studies have shown that TLR4 overactivation leads to insulin resistance and causes islet β-cell inflammatory infiltration and islet secretion dysfunction." (PMID 31934590, 2019). "The attenuation of steatosis and insulin resistance is most likely due to reduced pro-inflammatory gene expression in liver and adipose tissue of both global and liver-specific TLR4-deficient mice." (PMID 29666152, 2018). "Signalling through the pattern-recognition receptor TLR4, which is expressed on most cell types, has been associated with insulin resistance and beta-cell dysfunction in T2D." (PMID 30428550, 2018). "This correlates to abnormal TLR4 expression found in obese individuals, likely caused by increased free fatty acid levels which boost the likelihood of insulin resistance (Könner and Br üning, 2011)." (PMID 29922174, 2018). "In the present study we investigated the combined effects of high fat/high sucrose diet (HFD) feeding, ageing and TLR4-deficiency on tissue inflammation, insulin resistance and β-cell failure." (PMID 29426925, 2018). "TLR4 is thought to be an important mediator of obesity and insulin resistance because of its activation by saturated fatty acids and LPS, known to cause insulin resistance in adipose tissue amongst others." (PMID 28553556, 2017). "With a bone marrow transfer system, TLR4-deficient macrophages were shown to protect against diet-induced insulin resistance." (PMID 25923657, 2015). "TLR4-deficient mice and C3H/HeJ mice (which have a loss-of-function mutation in TLR4) are partially protected from fat-induced inflammation and insulin resistance in their visceral AT." (PMID 24741638, 2014). "Liver-specific PRSS8 knockout (LKO) mice develop insulin resistance associated with the increase in hepatic TLR4." (PMID 24614850, 2014). "TLR4 has also been implicated in promoting vascular insulin resistance by binding free fatty acids followed by subsequent activation of inflammatory pathways." (PMID 23840960, 2013). "This confirms other studies showing that TLR4 deficient mice are protected from insulin resistance induced by lipid infusion or a HFD." (PMID 23741455, 2013).
Insulin resistance (continued). "Corroborating with an important contribution of TLR-4 to muscle insulin resistance, mice containing a loss of function by mutation of this receptor are partially protected from fat-induced inflammation and insulin resistance." (PMID 22360800, 2012). "A mouse strain, CeH/HeJ, further supports this idea, as these mice have a mutation causing loss of function in TLR4 protecting them from diet-induced obesity and insulin resistance." (PMID 22970372, 2012). "It has been reported that loss of TLR4 protected against saturated fat-induced inflammation and insulin resistance." (PMID 21314942, 2011). "Further studies are needed to decipher the complex biomolecular mechanism linking consumption of diets rich in TF with pathologies associated with TLR4 signaling such as insulin resistance, metabolic syndrome, and type-2 diabetes." (PMID 21314942, 2011). "Further, it has been shown that TLR-4 deficiency protects mice from inflammation, insulin resistance, and increased adiposity in mice fed a diet high in SF." (PMID 21388548, 2011). "The specific TLR, TLR4 has been implicated in fatty acid induced inflammation and insulin resistance." (PMID 21314942, 2011). "Taken together, these data yet support our finding that a TLR4 variant impacts on body fat composition and insulin resistance." (PMID 21125016, 2010). "This gut derived inflammatory signal activates Toll like receptor 4, nuclear factor kappa B, and inflammasome associated pathways, linking barrier dysfunction to insulin resistance, hepatic steatosis, adipose tissue inflammation, endothelial activation, and vascular injury." (PMID 42280144, 2026). "Moreover, elevated TLR4 expression has been associated with insulin resistance, β-cell dysfunction, and progression of type 2 diabetes." (PMID 41598496, 2026). "Moreover, it was shown that the deficiency of its receptor, TLR4, decreases inflammation and insulin resistance in adipose tissue." (PMID 40216765, 2025). "Insulin resistance and reduction in skeletal muscles are associated with increased Toll-like receptor 4 (TLR4) expression and signaling in an aging model, which may be due to the development of secondary endotoxemia." (PMID 39668897, 2024). "The main contributors of this lipid class to the disease are ceramides, which are known to promote insulin resistance through inhibition of protein kinase B-mediated insulin signaling; ceramides have also been associated with toll-like receptor 4 dependent inflammation." (PMID 38999363, 2024). "Overactivation of TLR4 during chronic neuroinflammation reduces insulin sensitivity and causes insulin resistance, directly through pro-inflammatory kinases and reactive oxygen species, or indirectly through the release of pro-inflammatory cytokines and insulin-desensitizing factors." (PMID 39830652, 2024). "Moreover, TLR4 gene deletion has been showed to protect against insulin resistance in mice fed with a high fat diet, thus pointing at a causal role played by TLR4 in metabolic dysregulations." (PMID 37964189, 2023). "An increase in LPS activates the TLR4 signaling pathway to cause insulin resistance." (PMID 37143119, 2023). "Therefore, TLR4 is not only a key receptor in the inflammatory pathway but is also implicated in the development of insulin resistance." (PMID 36499769, 2022). "A2HS is also a toll-like receptor-4 activator linked to insulin resistance and inflammation." (PMID 36619946, 2022). "Several reports have documented that TLR2 and TLR4 signaling pathways could induce vascular inflammation and insulin resistance, leading to a higher risk of atherosclerosis." (PMID 35872802, 2022). "Therefore, the inhibition of TLR4 by Klotho contributes to the protection of tissues against inflammation-associated injury and insulin-resistance, especially because TLR4 is involved in generating oxidative stress." (PMID 33478014, 2021).
Insulin resistance (continued). "Finally, fetuin-A is implicated in lipid-induced insulin resistance by acting as an intermediary between palmitate and toll-like receptor 4 (TLR4) leading to adipose tissue inflammation and insulin resistance." (PMID 33192574, 2020). "In older adults, serum LPS and gene expression of its receptor, Toll-like receptor-4 (TLR4), is linked to lower insulin sensitivity compared to younger groups, showing that age-related LPS levels may increase the incidence of insulin resistance during aging." (PMID 32751533, 2020). "The hyperleptinemia associated with insulin resistance could play a role in the hydrolysis of fat to free fatty acids that act as a ligand for TLR4." (PMID 32708841, 2020). "These associations reflect the roles of TLR2 and TLR4 in the progress of insulin resistance and inflammation which in turn may lead the advance of nephrotic disease to the end-renal disease stage and renal failure." (PMID 33442388, 2020). "Therefore, subjects with TC haplotype carriers and with upregulated TLR4 protein expression are at increased risk for the pathogenesis of insulin resistance and MeS in obese subjects." (PMID 32708841, 2020). "Furthermore, this is supported by a study showing that TLR4 deficiency can prevent insulin resistance in lipid-infused male mice." (PMID 30863401, 2019). "However, mice deficient in toll-like receptor 4 (TLR4) or TNF receptor with high-fat-diet still show significant insulin resistance." (PMID 31447776, 2019). "TLR4 activation in adipocytes causes chronic inflammation and systemic insulin resistance." (PMID 31263454, 2019). "This is important because chronic inflammation in obese individuals is associated with muscle insulin resistance, and it could be hypothesised that the tenascin-C/TLR4 signalling axis is also involved in this response." (PMID 29137117, 2017). "Furthermore hepatic inflammation, lipid peroxidation and insulin resistance were markedly reduced in mice deficient for TLR4 suggesting a role for LPS and TLR4 in steatohepatitis mouse models." (PMID 27992443, 2016). "Interestingly, pro-inflammatory cytokines such as TNF-α and IL-6, key players of the TLR4 signaling pathways, have also been implicated in the pathogenesis of impaired glucose uptake and insulin resistance in humans and rodents." (PMID 26539824, 2015). "Furthermore, our longer 8 week HFD that led to muscle insulin resistance was only associated with a trend towards upregulation of Tlr-4 in soleus and a significant downregulation of Tlr-4 in TA muscle." (PMID 23951235, 2013). "ScN/Tie2-GFP mice, which lack a functional toll-like receptor 4 (TLR4), display lower fasting glucose and insulin levels and improved glucose tolerance compared to Tie2-GFP mice, suggesting that TLR4 deficiency decreases susceptibility to the development of insulin resistance." (PMID 23840960, 2013). "Thus, deletion or mutation of the gene encoding TLR4 was shown to protect against fatty acid-induced insulin resistance and diet-induced obesity." (PMID 22558381, 2012). "Further, we hypothesize that a loss of function mutation in TLR4 may protect against high TF diet-induced inflammation and insulin resistance in mice." (PMID 21314942, 2011). "Briefly, TLR4 activation by either lipopolysaccharides or fatty acids leads to metabolic inflammation and insulin resistance via NF‐κB signaling axis, while estrogen deficiency or impaired estrogen signaling is associated with insulin resistance and dysregulation of metabolic homeostasis." (PMID 41190280, 2025). "Thus, the recent literature proposed how type 2 diabetes mellitus risk may be related to a specific molecular pathway associated to Toll-like receptor 4 (TLR-4), generating insulin resistance." (PMID 38541047, 2024). "Therefore, deletion or mutation of the gene encoding TLR-4 may protect against fatty acid-induced insulin resistance and T2DM." (PMID 37009872, 2023).
Insulin resistance (continued). "TLR4 signaling was found essential for lipid-induced hypothalamic ceramide accumulation, and TLR4 deficiency in mice prevents hypothalamic ceramide accrual in response to lard oil infusion, protecting the animals from fatty acid-induced insulin resistance and systemic glucose intolerance." (PMID 35789435, 2022). "In the liver, these compounds can activate TLRs (TLR4), leading to hepatic inflammation, and in particular to the activation of liver resident macrophages (Kupffer cells), the first immune cells implicated in hepatic insulin resistance and in the development of steatohepatitis." (PMID 36078124, 2022). "Thus, rs180079 variant mediated increased IL6 expression may contribute to insulin resistance via TLR4 activation." (PMID 33820928, 2021). "In the present study, higher expression of TLR2 and TLR4 in diabetic patients with kidney failure than in diabetic patients without kidney failure was associated with higher values of HOMA-IR (as indicator of insulin resistance) and lower values of HOMA-IS (as indicator of insulin sensitivity)." (PMID 33442388, 2020). "Therefore, the objective of this current study was to investigate whether loss of function mutation in TLR4 protects against TF rich diet-induced inflammation and insulin resistance in a mouse model." (PMID 21314942, 2011). "We described inSection 1.4.3 how TLR4 might beinvolved in the inflammation occurring in the obese state, and recent studiesreported a protection of high-fat fed mice against insulin resistance andvascular inflammation in TLR4-deficient mice compared to WT animals." (PMID 18350123, 2008). "Experiments confirm that BAL alleviates local ovarian inflammation and insulin resistance by inhibiting the LPS/TLR4/NF-κB signaling pathway, thereby improving PCOS pathological manifestations." (PMID 42294648, 2026). "TLR4 activation, in response to elevated circulating free fatty acids (FFAs) and endotoxins, promotes chronic low-grade inflammation, insulin resistance, and hepatic lipid accumulation, all of which are key features of MASLD." (PMID 41598496, 2026). "This persistent TLR4 activation contributes to prolonged low-grade inflammation, insulin resistance, and β-cell injury in T2D." (PMID 40871736, 2025). "Adipose tissue—particularly visceral fat—secretes inflammatorycytokines (e.g., IL-6, TNF-α), activating the TLR4/NF-κBpathway, which induces insulin resistance, endothelial dysfunction, andatherosclerotic plaque formation." (PMID 41356294, 2025). "Fetuin-A is a hepatokine that contributes to MASLD pathogenesis primarily by promoting insulin resistance and amplifying TLR-4 (toll-like receptor 4)—mediated inflammatory signaling, thereby linking metabolic disturbances with hepatic steatosis and fibrosis." (PMID 40943908, 2025). "Recently, we identified lipotoxic Hep-sEVs as transporters of saturated fatty acids (SFAs) and potent inducers of liver inflammation and insulin resistance in this organ by a mechanism dependent on macrophage Toll-like receptor 4 (TLR4)." (PMID 40387904, 2025). "In murine models, high levels of fatty acids can activate TLR4 signaling in fat cells and macrophages, resulting in insulin resistance." (PMID 40076851, 2025). "Lactobacillus acidophilus reduces body weight, fat mass, inflammation, and insulin resistance and inhibits the toll-like receptor 4 (TLR4)/NF-κB signaling pathway." (PMID 40362711, 2025). "This promotes insulin resistance via lipopolysaccharide–Toll-like receptor 4 (TLR4) signaling pathways." (PMID 40943638, 2025). "An isoleucine-restricted diet effectively prevented HFD-induced NAFLD and metabolic disorders by modulating intestinal flora, reducing LPS production, inhibiting the TLR4/NF-κB inflammatory pathway, and improving insulin resistance." (PMID 41048505, 2025). "TLR4-mediated insulin resistance can be attributed to the NF-κB and mitogen-activated protein kinases (MAPK) signaling pathway." (PMID 40076851, 2025).